WNT5A (Wnt family member 5A)
Diseases named in the same sentence as WNT5A in open-access papers (continued):
Sharing a sentence is not in itself a finding about the gene and the disease.
asthma (continued). "Interestingly, experiments with both two types of cell lines led to the conclusion that MMP10 may activate canonical Wnt signaling by inhibiting Wnt5a, which led to our further prediction that MMP10 might be also associated with Wnt/β-catenin in asthma." (PMID 35000533, 2022). "Therefore, we have generated a tetracycline-based (tet-ON) smooth-muscle-specific WNT5A transgenic mouse model, enabling in vivo characterization of the relevance of smooth-muscle derived WNT5A in an allergic asthmatic context, using chronic ovalbumin exposure to drive asthma-like changes." (PMID 32317758, 2020). "Expression of WNT3, WNT5a, WNT10, and their receptor, Fzd-5, positively correlated with type 2-high asthma in adults whereas expression of WNT5b negatively correlated with type 2 inflammation." (PMID 37814791, 2023). "Eosinophils enhance Wnt-5a, TGF-β1, fibronectin, and collagen gene expression in ASMC and promote proliferation of these cells in asthma." (PMID 27297409, 2016). "It is also important to note that we have not confirmed the change in bronchial epithelium Wnt5a in the animal model of asthma." (PMID 38898476, 2024). "The study’s novelty lies in identifying the Wnt5a-mediated Ca2+/CaMKII axis as a potential therapeutic target for treating EMT in asthma, offering new avenues for research and treatment strategies in managing asthma-related airway remodeling." (PMID 38898476, 2024). "Next, we assessed the relationship between Wnt5a and EMT in HBECs from asthma patients." (PMID 38898476, 2024). "While these results highly suggest that WNT5A drives airway inflammation and remodelling in asthma, conclusive evidence is still lacking to confirm this." (PMID 32317758, 2020). "As activated and non-activated asthmatic eosinophil increased WNT-5A expression without significant differences in the asthma group, we presume that the WNT-5A signaling pathway was not the major signaling pathway responsible for changes in ASM cell activity." (PMID 32155894, 2020). "Still, it is not known how WNT-5A signaling is changed during acute asthma, but there is an increased expression of WNT-5A in asthmatic ASM cells." (PMID 32155894, 2020). "Eosinophils from patients with asthma have much greater activity and more efficaciously enhance the production of TGF-β1 in ASMC, which in turn may affect Wnt-5a gene expression." (PMID 27297409, 2016). "We hypothesized that eosinophils promote ASMC proliferation through elevated ECM protein (fibronectin and collagen) production induced by altered Wnt-5a and TGF-β1 expression in asthma." (PMID 27297409, 2016). "While it has not been reported whether the Wnt5a signaling pathway may be involved in the EMT of HBECs during asthma." (PMID 38898476, 2024). "Wnt5a, a prototype of a non-canonical Wnt signaling axis with known cross talk with TGFβ1 during repair and remodeling, was elevated in the airway epithelium of Th17 asthma patients and steroid-resistant asthma." (PMID 33791298, 2021). "Additionally, it was shown that non-canonical WNT-5A signaling is important in TGF-β induced ECM production by ASM cells in asthma." (PMID 32155894, 2020). "We have recently reported increased WNT-5A expression in asthmatic airway smooth muscle cells and have demonstrated that TGF-β induces WNT-5A expression in airway smooth muscle cells where it mediates expression of extracellular matrix proteins (ECM) and participates in airway remodeling in asthma." (PMID 26514730, 2016).
bladder cancer (23 papers, 1998 to 2025). "In conclusion, our results demonstrate that BMP2 enhances tumor growth and angiogenesis in a mouse bladder cancer model, likely through the induction of WNT5A and modulation of endothelial cell behavior." (PMID 40552583, 2025). "As proof, osteogenesis driven by the betaglycan–Wnt5a circuit is apparent within bladder cancer, while exosomes secreted by adipocytes in breast cancer stimulate tumor growth via Hippo signaling activation." (PMID 39861125, 2025). "Numerous researches have demonstrated the detrimental role of WNT5A, a protein involved in cell signaling, in driving chemotherapy resistance and promoting the expression of stemness markers in bladder cancer cells." (PMID 38430246, 2024). "The SE-related oncogene SOX4 can either indirectly or directly suppress WNT5a levels, and WNT5a most likely protects bladder cancer cells from invasion." (PMID 37501079, 2023). "For instance, SOX4 overexpression facilitated tumor aggressiveness in bladder cancer by regulating cellular invasion via repressing WNT5a expression." (PMID 33854048, 2021). "This suggests that SOX4 may regulate WNT5a levels either directly or indirectly, and WNT5a play a protective role in preventing invasion in bladder cancer cells." (PMID 40635786, 2025). "Mechanistic studies revealed that the SLC14A1+ subtype of CAF in bladder cancer originates from interferon-stimulated differentiation and can secrete WNT5A, thereby activating the Wnt pathway in bladder cancer cells in a paracrine manner and enhancing tumor cell stemness." (PMID 39061061, 2024). "SOX4 regulates invasion of bladder cancer cells via repression of WNT5a." (PMID 38520027, 2024). "In bladder cancer, SLC14A1+ CAFs produce WNT5A to confer stemness to bladder tumor cells, in turn tumor cells drive interferon production to enhance SLC14A1+ CAF differentiation." (PMID 38773979, 2024). "EV-packaged BCYRN1 secreted by bladder cancer cells epigenetically increases WNT5A expression, thereby facilitating VEGF-C secretion, and forms an WNT5A/VEGF-C/VEGFR3 feedforward loop that enhances lymphangiogenesis." (PMID 36971125, 2023). "The expression of one transforming (Wnt7b) and one non-transforming (Wnt5a) Wnt gene in four human bladder carcinoma cell lines, and in normal human bladder tissues (n = 8) and bladder cancers (n = 48) were analysed by ribonuclease protection analysis." (PMID 9461004, 1998). "The downregulation of Wnt pathway-related proteins such as Wnt5a/b, DVL2, LRP-6, and phosphorylated LRP-6 upon POLR3G knockdown was further confirmed by Western blotting, indicating that POLR3G might influence bladder cancer behavior through the Wnt signaling pathway." (PMID 39039528, 2024). "The downregulation of Wnt pathway-related proteins such as Wnt5a/b, DVL2, LRP-6, and phosphorylated LRP-6 upon POLR3G knockdown was further confirmed by Western blotting, indicating that POLR3G may affect bladder cancer behavior through the Wnt signaling pathway." (PMID 39039528, 2024).
psoriasis (23 papers, 2009 to 2026). An autoimmune condition characterized by red, well-delineated plaques with silvery scales that are usually on the extensor surfaces and scalp. "WNT5a was reported to be several-fold upregulated in psoriasis skin lesions and has been identified as one of five key genes associated with psoriasis pathogenesis." (PMID 40806307, 2025). "The key cell cycle regulatory protein F-box protein S-phase kinase-associated protein 2 (SKP2) was significantly downregulated, along with the psoriasis-associated proliferation marker WNT5a, identified as a SKP2 downstream target." (PMID 40806307, 2025). "IL-17A was a crucial factor associated with abnormally upregulated Wnt5a expression during psoriasis development." (PMID 40365308, 2025). "Conversally, PPARγ inhibits STAT3 which, when overexpressed, induces Wnt5a and causes a psoriasis-like phenotype in vivo." (PMID 19399181, 2009). "Finally, the neutrophil aggregates in the stratum corneum, a hallmark of psoriasis, also express Wnt5a (arrow)." (PMID 19399181, 2009). "Gene Ontology (GO) molecular function analysis showed that TP treatment significantly affected skin development in the mice and downregulated the expression of Wnt5a, which is highly expressed in the skin lesions of patients with psoriasis." (PMID 40365308, 2025). "PCNA is used to examine epidermal hyperproliferation in psoriasis and the potential for malignancy in skin lesions, and CCD1 is a key regulator of cell cycle progression in psoriasis, and both are downstream of the Wnt5a/β-catenin pathway genes." (PMID 40365308, 2025). "Owing to IMQ-induced psoriasis, Wnt5a expression was upregulated in mice similar to in patients with psoriasis." (PMID 40365308, 2025). "Herein, the IMQ-induced psoriasis model mice showed a similar increase in Wnt5a and β-catenin mRNA expression and protein levels and Wnt5a mRNA expression in skin development classification was downregulated by TP treatment." (PMID 40365308, 2025). "It was also reported that the reduction of Wnt5a+ fibroblasts is an early change in the resolution of skin inflammation after systemic or topical treatment in patients with psoriasis." (PMID 40574847, 2025). "We previously found that components of the Wnt signaling pathway, and specifically WNT5a, were strongly differentially hypomethylated in the epidermis of psoriasis patients compared to controls." (PMID 40806307, 2025). "TP alleviated psoriasis in mice by exerting anti-inflammatory effects and inhibited keratinocyte proliferation, which was partly achieved by regulating the Wnt5a/β-catenin signaling pathway." (PMID 40365308, 2025). "We generate a high-resolution atlas of early disease resolution, identifying a pro-inflammatory WNT5A+/IL24+ fibroblast state that is enriched in psoriasis lesions." (PMID 38291032, 2024). "To validate the pathogenic involvement of WNT5A+/IL24+ fibroblasts, we sought to detect these cells in other psoriasis datasets generated in the first two weeks of treatment." (PMID 38291032, 2024). "Taken together, these observations identify the reduction of WNT5A+/IL24+ fibroblasts as an early event mediating the resolution of skin inflammation in psoriasis, following systemic or topical treatment." (PMID 38291032, 2024). "The analysis of these samples confirmed that WNT5A+/IL24+ fibroblasts are only detectable in lesional psoriasis skin, where their abundance begins to decrease after one week of treatment." (PMID 38291032, 2024). "In as early as 2010, it was indicated that altered Wnt signaling played an important role in psoriasis, as Wnt-5a was upregulated in psoriatic lesions, whereas WIF-1 was downregulated." (PMID 38008779, 2023). "Wnt/β-Catenin and WNT5A/Ca pathways regulate proliferation and apoptosis of keratinocytes in psoriasis lesions." (PMID 36387067, 2022).
psoriasis (continued). "Of the WNT proteins, WNT5a is the one most extensively studied in psoriasis and has been suggested to have a role in inducing the marked vascular changes, epidermal proliferation, and amplification of inflammatory responses seen in lesional skin." (PMID 31089877, 2019). "There is evidence for altered Wnt signaling in psoriatic skin, with higher Wnt5a expression in psoriatic plaques While anti-TNFα treatment decreases WNT5A gene expression to less than 75%, WNT5A remains part of the molecular profile of resolved psoriasis." (PMID 26849645, 2016). "The relationship between Wnt5a and β-catenin signalling in psoriasis as well as physiological epidermal turn-over is unclear." (PMID 19399181, 2009). "In line, Wnt5a and fzd5 are both overexpressed and re-distributed in the epidermis of psoriasis which involves disturbed keratinocyte differentiation." (PMID 19399181, 2009). "Third, WNT5a induces epithelial differentiation and stimulates endothelial cell proliferation, both important elements of psoriasis." (PMID 19399181, 2009). "Fourth, Wnt5a is upregulated in wound healing and psoriasis lesions can classically be triggered by skin wounding." (PMID 19399181, 2009). "Wnt5a was found significantly upregulated on the mRNA level in keratinocytes derived from psoriasis patients." (PMID 19399181, 2009). "We included Fzd3 and Fzd5 in this analysis, since these have been reported to bind Wnt5a, as well as Fzd6, as it was found upregulated in psoriasis and squamous cell carcinoma." (PMID 19399181, 2009). "We next characterized the expression of Wnt5a, Fzd3, Fzd5, Fzd6 in psoriasis lesions which are characterized by hyperproliferation and dysregulated differentiation." (PMID 19399181, 2009). "Before analyzing Wnt5a expression in psoriasis on the protein level, we first performed a detailed immunohistochemical expression analysis in normal adult human skin which has not been published to date." (PMID 19399181, 2009). "APP is upregulated and re-distributed in psoriasis lesions strikingly similar to Wnt5a and APP stimulates both proliferation and mobility of keratinocytes." (PMID 19399181, 2009). "Mechanically, TP inhibits Wnt5a/β-catenin signaling, which may be a potential mechanism by which TP improves psoriasis." (PMID 40365308, 2025). "Furthermore, we investigated the relationship between Wnt5a and IL-17A in psoriasis to provide a novel theoretical basis for the clinical application of TP and new targets for psoriasis treatment." (PMID 40365308, 2025). "Therefore, we propose that TP suppresses keratinocyte hyperproliferation and inflammatory responses in psoriasis by regulating the Wnt5a/β-catenin signaling pathway." (PMID 40365308, 2025). "Interestingly, a closer inspection of single-cell profiles identified some differences between prurigo nodularis and psoriasis lesions, with WNT5A+/IL24+ fibroblasts expressing TBX3 and CXCL8 only in the latter." (PMID 38291032, 2024). "To understand whether WNT5A+/IL24+ fibroblasts are present in other inflammatory skin diseases beyond psoriasis, we sought to detect these cells in publicly available scRNA-seq datasets." (PMID 38291032, 2024). "In our study, the differentially expressed gene WNT5A was classified as an atypical Wnt family member, which is associated with human skin diseases such as psoriasis, papulosquamous skin disease, and non-melanoma skin cancer." (PMID 35864447, 2022). "Pharmacological inhibition of Wnt5A, for example, may remediate inflammation and other symptoms in arthritis or psoriasis patients." (PMID 27833613, 2016). "The transcriptional upregulation of Wnt5a itself is unlikely to cause invasiveness, since it is also strongly upregulated in psoriasis, a hyperproliferative but non-invasive disorder." (PMID 22384081, 2012). "Taken together, Wnt5a, Fzd5, and Fzd6 are strongly upregulated in psoriasis." (PMID 19399181, 2009). "We and others have previously found Wnt5a to be upregulated on the mRNA level in psoriasis." (PMID 19399181, 2009).
psoriasis (continued). "Functionally, Wnt5a lowers the concentration of IFN required to induce target genes, and increases the magnitude of IFN target gene induction, suggesting a molecular mechanism underlying IFN hypersensitivity in psoriasis." (PMID 19399181, 2009). "The marked overexpression of Wnt5a and Fzd5 in psoriasis suggest that this ligand-receptor pair may actively drive the chronic inflammatory and hyperproliferative nature of this phenotype." (PMID 19399181, 2009). "First, WNT5a induces IL12, which is central to psoriasis, as indicated by the therapeutic efficacy of antibodies targeted at IL12p40 and by the genetic association of IL12 with psoriasis." (PMID 19399181, 2009). "Here, we show that Wnt5a and its putative receptors are localized to specific compartments in normal skin and that Wnt5a is both highly upregulated and re-distributed in the hyperproliferative epidermis in psoriasis." (PMID 19399181, 2009). "Wnt5a signalling in psoriasis may also be related to the activation of the nuclear hormone receptor PPARδ which we have previously identified as a central mediator in psoriasis." (PMID 19399181, 2009). "In a previous study, psoriasis lesions were investigated through biopsy and examining WNT molecules of the WNT/β -catenin pathway and the authors determined that Wnt5a levels were elevated 4-fold in the lesional skin." (PMID 39910492, 2025). "Taken together, our observations identify WNT5A+/IL24+ fibroblasts as an IL-17/TNF dependent, inflammatory cell state, that in psoriasis, is rapidly normalized by IL-23 blockade." (PMID 38291032, 2024). "A key result from our study is the identification of a WNT5A+/IL24+ inflammatory fibroblast state, which is expanded in lesional psoriasis skin and rapidly shrinks after treatment initiation." (PMID 38291032, 2024). "We confirmed that HES1 is significantly decreased in the epidermis of psoriasis patients and IMQ-induced mouse model, which is probably due to the interaction between Wnt5a and Notch141." (PMID 36535970, 2022). "Wnt5a was also reported to be significantly higher in lean patients with psoriasis compared with lean healthy controls and in obese patients compared with obese healthy controls suggesting that, in psoriasis, an increase in wnt5a may contribute to the development of metabolic comorbidity." (PMID 25977937, 2015). "Second, Wnt5a is itself strongly induced by STAT3, thereby acting as a potential effector molecule for the psoriasis-like skin disease seen in STAT3-overexpressing transgenic mice." (PMID 19399181, 2009). "Thus, Wnt5a and β-catenin activation may occur concurrently in psoriasis." (PMID 19399181, 2009). "Both WNT5A and IL24 are overexpressed in psoriasis skin lesions." (PMID 38291032, 2024). "Likewise, the analysis of future datasets of treatment responses will establish if WNT5A+/IL24+ fibroblasts undergo dynamic, treatment-dependent shifts in other inflammatory skin diseases beyond psoriasis." (PMID 38291032, 2024). "We identified one PP-decreased DEM with genes biased towards hyper-methylation in psoriasis lesions (i.e., PTEN-28; P = 0.01; FDR = 0.16; GSEA), along with two PP-increased DEMs with genes biased towards hypo-methylation (i.e., STAT3-30 and WNT5A-48; P≤0.023; FDR ≤0.23; GSEA)." (PMID 24260178, 2013). "If this finding is confirmed in future cohorts, the frequency of WNT5A+/IL24+ cells could be monitored in the increasing number of patients receiving biologics, with the potential to inform personalized, drug tapering strategies in psoriasis remission." (PMID 38291032, 2024). "Mice with overexpression of Wnt5a in the epidermis do not exhibit a psoriasis phenotype." (PMID 31313518, 2019). "The overexpression of Wnt5A and Fzd5 in psoriasis may denote the targeting of non-canonical Wnt pathway elements as an efficacious tactic in the remediation of psoriatic symptoms." (PMID 27833613, 2016).
psoriasis (continued). "Therefore, the induction of APP by Wnt5a/IFN may contribute to increased keratinocyte turnover and migration in psoriasis." (PMID 19399181, 2009).